METAP2 (methionyl aminopeptidase 2)
Diseases named in the same sentence as METAP2 in open-access papers (continued):
Sharing a sentence is not in itself a finding about the gene and the disease.
tumor (26 papers, 2007 to 2026). "Methionine aminopeptidase 2 (MetAP2) is essential to endothelial cell growth and proliferation during tumor angiogenesis." (PMID 37637935, 2023). "M8891, which belongs to a novel class of selective and reversible MetAP2 inhibitors, has been shown to have strong anti-tumor activity in vivo." (PMID 37798538, 2023). "M8891 plasma concentration showed dose-linear increase up to 35 mg and low-to-moderate variability; dose-dependent tumor accumulation of methionylated elongation factor 1α, a MetAP2 substrate, was observed, demonstrating MetAP2 inhibition." (PMID 37637935, 2023). "MetAP2 has been shown to play an essential role in the growth and proliferation of endothelial cells during tumor angiogenesis and tumor cell proliferation." (PMID 37637935, 2023). "MetAP2 is an intracellular metalloprotease crucial in tumourigenesis and tumour microenvironment homeostasis." (PMID 35159167, 2022). "Synthetic NBD peptide blocked the interaction between S100A4 and MetAP2 in endothelial cells and inhibited tumor angiogenesis and prostate cancer growth in tumor-bearing mice." (PMID 34209679, 2021). "Methionine aminopeptidase 2 (MetAP2) positively regulates endothelial cell proliferation during tumor angiogenesis." (PMID 34966277, 2021). "The results from the histological analyses of the tumor tissues revealed a high MetAp2 expression, with detectable sites of co-localization with lymphatic capillaries." (PMID 32708166, 2020). "In a recent study, the methionine aminopeptidase MetAP2 was LV knocked down in tumor cells resulting in reduced angiogenesis and tumor growth, positively affecting survival of mice." (PMID 30909628, 2019). "As higher MetAP2 expression was observed in tumor (mesothelioma, neuroblastoma, and colorectal carcinoma) cells compared with normal cells, the enzyme serves as a target for anti-angiogenic compounds of natural origin, such as fumagillin and ovalicin." (PMID 30034623, 2018). "Fumagillin has been shown to target MetAP2 in a highly specific manner, inducing an anti-tumor effect." (PMID 27542228, 2016). "MetAP2 plays a critical role in the proliferation of endothelial cells and certain tumor cells and thus serves as a promising target for anti-angiogenesis and anticancer drugs." (PMID 19703310, 2009). "A reversible MetAP-2 inhibitor was also reported to lead to endothelial cell cycle arrest and to exhibit efficacy in a range of murine tumour models." (PMID 18072970, 2007). "Other MetAP-2 inhibitors have been described as inhibiting tumour growth in mice, and to induce accumulation in endothelial cells of the cyclin-dependent kinase inhibitor p21WAF1/Cip1." (PMID 18072970, 2007). "Additionally, potential anti-tumor cellular mechanisms were explored through molecular docking, which was used to predict the binding mode of 4c with METAP2 and EGFR, suggesting that the C=O part of the pyridone moiety likely played a crucial role in binding." (PMID 39273581, 2024). "Inhibition of the enzymatic activity of MetAP2 leads to a variety of changes in protein functionality impacting both tumor growth and proliferation, as well as, by acting directly on endothelial cells, inhibiting angiogenesis in a vascular endothelial growth factor (VEGF)-independent manner." (PMID 37798538, 2023). "Finally, we decided to further investigate Usp7, Metap1 and Metap2 due to most distinct effects in the first validation assays and literature postulating tumor-promoting functions of these proteases 62-73." (PMID 35673573, 2022). "MetAP-2 inhibition could have a combined effect on endothelial cells, with an antiangiogenetic effect, and on tumour cells." (PMID 35159167, 2022). "Finally, we investigated the anti-tumor activity of MetAp2 inhibition in lymphangiogenic-rich tissues." (PMID 32708166, 2020). "Selective inhibition of MetAP2 stops vascularization and tumor growth in animal models." (PMID 30034623, 2018).
tumor (continued). "Hence, we reasoned that combining MetAP2 targeting treatment with redox-directed therapeutics would lead to more efficient antitumor activity on a wider spectrum of tumor." (PMID 27542228, 2016). "We suggest that MetAP1 levels could be routinely checked in several types of tumor and used as a prognostic marker for predicting the response to treatments inhibiting MetAP2." (PMID 27542228, 2016). "We suggest that MetAP1 expression could be routinely checked in several types of tumor, as a prognostic marker for predicting the efficacy of any treatments targeting MetAP2 activity and for the fine-tuning of therapeutic strategies." (PMID 27542228, 2016). "Furthermore, METAP2 inhibition may provide prevention of tumor cell growth, development and progression in NSCLC patients." (PMID 32922205, 2020). "Several studies have reported its anti-tumor activity against UBC since Shim and coworkers firstly identified NTX as an antiangiogenic agent in UBC through inhibition of methionine aminopeptidase-2 (MetAP2) 19-21." (PMID 34421363, 2021). "We performed cell growth assays with various mammalian primary, immortalized or tumor cell lines, including endothelial, non-tumor and tumor-derived lines with and without fumagillin treatment, to determine the precise selectivity of the MetAP2 inhibition phenotype." (PMID 27542228, 2016).
infection (3 papers, 2015 to 2023). The state of being infected such as from the introduction of a foreign agent such as serum, vaccine, antigenic substance or organism. "Furthermore, miRNAs of interest may be overexpressed (gain-in-function) in cell lines through a lentiviral infection or plasmid transfection to determine their effect on NMT1/NMT2/METAP2 mRNA transcript levels using qPCR and the resulting protein expression by Western blot analysis." (PMID 29579063, 2018).
metabolic disease (2 papers, 2019 to 2024). A congenital disorder (due to inherited enzyme abnormality) or acquired (due to failure of a metabolically important organ) disorder resulting from an abnormal metabolic process. "Future research should focus on exploring how MetAP2 inhibition affects these signaling pathways to substantiate its role as a therapeutic target for metabolic disorders." (PMID 39766279, 2024). "The role of MetAP2-dependent N-myristoylation in regulating metabolic pathways provides a promising avenue for managing metabolic diseases." (PMID 39766279, 2024). "The connection between MetAP2 and metabolic disorders is further supported by studies in adipose tissue." (PMID 39766279, 2024). "This review synthesizes existing research to suggest possible signaling pathways through which MetAP2 inhibition might beneficially affect these metabolic disorders." (PMID 39766279, 2024). "Continued research into the molecular mechanisms of MetAP2 and its role in metabolic diseases may lead to safer and more effective treatments." (PMID 39766279, 2024). "This review aims to deliver a comprehensive analysis of MetAP2 and its role in metabolic diseases." (PMID 39766279, 2024). "The pharmacological inhibition of MetAP2 has demonstrated the ability to reduce body weight, enhance glucose tolerance, and improve lipid profiles in preclinical models, making it an attractive target for managing metabolic disorders." (PMID 39766279, 2024).
brain disorder (1 paper, 2025). A disease affecting the brain or part of the brain. "While MetAP2 inhibitors generally alleviate multiple pathological conditions, the therapeutic potential of MetAP2 inhibitors in brain disorders has had limited studies despite the abundant presence of MetAP2 in the brain." (PMID 39942725, 2025). "Thus, our experiments demonstrate an anti-neuroinflammatory action of BL6, suggesting possible clinical applications of MetAP2 inhibitors for brain disorders in which neuroinflammation is involved." (PMID 39942725, 2025).
infectious disease (1 paper, 2018). A disorder directly resulting from the presence and activity of a microbial, viral, or parasitic agent in humans. "We found 14 miRNAs that were associated with functions in infectious diseases, 8 of which target NMT1/2 genes and 6 miRNAs target MetAP2 gene." (PMID 29579063, 2018). "Furthermore, miR-140, miR-628-3p and miR-943 miRNAs that target NMT1/2 and MetAP2 genes were found to have roles in infectious diseases." (PMID 29579063, 2018). "Specifically, studying miRNA interactions with the NMT1/2 and MetAP2 genes will shed light on the poorly understood regulation of myristoylation, a key cellular function critical to oncogenesis, adaptive immune function, and infectious disease onset." (PMID 29579063, 2018).
METAP2 also shares sentences with these, for which no sentence is quoted: ovarian carcinoma (3 papers); colorectal cancer (2); Prader-Willi syndrome (2); acute myeloid leukemia (1); Autoimmunity (1); B-cell lymphomas (1); bladder cancer (1); breast (1); cervical cancer (1); esophageal cancer (1); gastric cancer (1); glioma (1); Hypoglycemia (1); kidney adenocarcinoma (1); malignant mesothelioma (1); myeloma (1); myotonic dystrophy (1); rhabdomyosarcoma (1); Sepsis (1); triple-negative breast carcinoma (1); type 2 diabetes (1).